AR (androgen receptor)
Diseases named in the same sentence as AR in open-access papers (continued):
Sharing a sentence is not in itself a finding about the gene and the disease.
tumor (continued). "This reciprocal cross-talk between the PI3K/AKT and AR pathways suggests that the combined inhibition of the AR and PI3K/AKT pathways may be necessary to achieve more complete tumor control and improve efficacy." (PMID 36297536, 2022). "However, a recent study identified AR as a tumor suppressor in ER-positive BRCA and supported AR agonism as the optimal AR-directed treatment strategy, revealing a rational therapeutic opportunity." (PMID 35880165, 2022). "Similarly, in patients, high pretreatment AR activity predicts the downregulation of MYC, tumor regression, and both progression-free and overall survival on BAT." (PMID 36194476, 2022). "AR expression is also found in 30–60% of non-ER expressing (ER-negative) tumours where the role of AR in radiosensitisation has previously been described." (PMID 35618789, 2022). "Moreover, the oncogenic role of AR, ER, GR, PPAR and VDR in tumor-supporting cells is well characterized." (PMID 36142861, 2022). "Furthermore, despite the reduction in tumor burden upon CSF1R blockade, there was a minimal change in the expression of AR, pERK, p-GSK, VEGF, ARV7, and Ki67." (PMID 36209194, 2022). "FOXA1 is essential for AR reprogramming towards a cancerous phenotype and its overexpression, together with that of HOXB13, leads to a shift in the AR cistrome in an immortalized prostate epithelial cell line towards a tumor-like phenotype." (PMID 35682963, 2022). "Regardless of castrate levels of testosterone, tumor cells can proliferate due to clonal selection of cells with AR amplification." (PMID 35686097, 2022). "We then examined the consequence of hypoxia-suppressed AR signaling on the RCC progression, with a focus on CSC phenotype, as abundant evidence indicated that CSC might play important roles for tumor development and progression." (PMID 36397101, 2022). "Without taking gender into account, AR protein expression levels were statistically significantly different between the tumor core and the enhancing tumor region (p = 0.0386078), as well as between the tumor core and peritumoral area (p = 0.0056848)." (PMID 36361793, 2022). "Considering only patients in whom circulating tumor cells were detected, 75% did not express ARV7 or AR full length splice variants, while all patients expressed PSMA and 75% of patients had PSA positive CTCs." (PMID 35763249, 2022). "In our study, no sex differences were observed in the expression of AR in the tumours, prompting us to the conclusion that the AR gene does not escape X chromosome inactivation in GBM." (PMID 35661403, 2022). "TNBCs' are aggressive tumours with poor prognosis and have been reported to express High molecular weight cytokeratin (CK5/6, CK14 & CK17), epidermal growth factor receptor (EGFR), E-cadherin, and Androgen receptors (AR)." (PMID 35463732, 2022). "Notably, only patients with preBAT ARAMW scores greater than 0.6 exhibited a significant decrease in MYC protein expression, supporting the concept that high preBAT AR activity is required for downregulation of MYC and tumor regression by SPA." (PMID 36194476, 2022). "AR drives the expression of two key enzymes, ornithine decarboxylase (ODC1) and the SAM-decarboxylase AMD1, thus elevating polyamine to levels necessary for transformation and tumor progression." (PMID 36358940, 2022). "Our in vitro and in vivo results shed light on the role of TRPM8 on PCa AR–negative tumor growth and metastasis dissemination." (PMID 35743115, 2022). "Interaction between androgen and the HER-2 signalling pathway in hormone receptor negative tumours has been demonstrated with impaired cell growth following AR blockade." (PMID 34537861, 2022).
tumor (continued). "In addition, the immunohistochemical results showed the altered staining patterns of BCOR, bcl2, CyclinD1, TLE1, AR, SMA, CD117, STAB2, CD56, and CD99 in tumor tissues after chemotherapy." (PMID 35568949, 2022). "Indeed, several studies have demonstrated that the androgen receptor (AR) remains active in CRPC, playing an important role in tumor function and growth." (PMID 36348374, 2022). "We cannot entirely rule out that the low AR/NKX3.1/HOXB13 tumor cells at baseline were selected for by enza treatment." (PMID 36109521, 2022). "It was also found that the oncogenic lncRNA CCAT1 promotes PC cell proliferation and tumor growth of PC xenotransplantation, acting as a scaffold for the DDX5 and AR transcriptional complex to facilitate the expression of AR-regulated genes in nuclei, thus stimulating PC progression." (PMID 35954483, 2022). "Moreover, Fisetin attenuated tumor growth and reduced serum PSA levels by competing with the AR ligand and decreasing AR stability in a CWR22 Rupsilon1 cell xenograft model in athymic nude mice." (PMID 36139145, 2022). "AR expression was negatively associated with PFS but not tumour size, tumour stage or pathological grade." (PMID 35452181, 2022). "True de novo neuroendocrine prostate cancer, AR-negative and androgen-independent, is very rare and yet, in recent years, the increasing emergence of neuroendocrine-like tumour phenotypes late in disease course has been noted." (PMID 34535657, 2021). "Non-neoplastic, non-apocrine cells present around the tumour showed AR monosomy in two cases, in 15.73% and 4.17% of the cell population respectively." (PMID 33534004, 2021). "Similar to previous studies of intense AR signaling inhibition, we found 25% of patients demonstrated complete response or near CR, with the remainder displaying either partial tumor regression or no histologic evidence of response." (PMID 34322653, 2021). "TRIM proteins affect PC in a variety of ways, acting in a tumor suppressive or oncogenic fashion, reaching from biomarkers for diagnosis to influencing epithelial mesenchymal transition (EMT) and interactions with the AR, which will be further explained below." (PMID 34208621, 2021). "Therefore, in androgen-dependent PCa cells, ligand-mediated activation of AR can be downregulated by multiple hormone deprivation strategies that are implemented during ADT and their biochemical failure enables tumor recurrence and distant metastasis." (PMID 35582006, 2021). "Conversely, γδ T cell infiltration was not correlated with tumor size, nodal status, histological type, basal-like phenotype, PIK3CA1 mutations, and AR or FOXA1 expression." (PMID 33673133, 2021). "Furthermore, among patients with PD-L1-positive tumor, poorer relapse-free survival (RFS) and overall survival (OS) were observed in the case of co-expression of AR and FOXA1." (PMID 33915941, 2021). "Besides controlling AR and ARv7, USP7 is also in charge of the stability of the CCDC6 gene product, a tumor suppressor whose impairment induces a BRCAness-like phenotype which associates to PARP inhibitors sensitivity in prostate and urothelial cancer." (PMID 33546726, 2021). "AR expression level in normal urothelium did not correlate with tumor recurrence and tumor cell ERα and ERβ expression did not predict recurrence." (PMID 34768683, 2021). "AR is a key driver of PCa, and this study identifies another avenue to promote disease progression through regulation of CRY1, which further enhances DDR to promote genomic instability and tumor growth." (PMID 33452241, 2021).
tumor (continued). "Intravenous administration of the dual-drug carrying nanoparticles resulted in complete tumor regression of PSMA-expressing, androgen receptor-positive tumor xenografts, in contrast to animals that received an intravenous combination of both drugs in their free form." (PMID 33391494, 2021). "Moreover, IL-6 upregulates the expression of the androgen receptor and of CXCR4 on tumor cells, thereby favoring tumor cell proliferation and recruitment to bone via the CXCL12/CXCR4 axis." (PMID 34064859, 2021). "The subsequent down-regulation of AR signaling regulates MMP9 levels, in favor of tumor metastasis." (PMID 34831421, 2021). "Recently, clinical research has shifted the interest to AR as a possible therapeutic option in BC treatment, due to the high degree of presence on the tumor cells and lack of therapeutic drugs." (PMID 33802610, 2021). "Moreover, tumors with molecular apocrine phenotype, i.e., expressing both AR and FOXA1 biomarkers, exhibited significantly lower density of intra-tumor CD11b- or CXCR2-positive cells (p = 0.001 and p = 0.006, respectively)." (PMID 34066060, 2021). "Therefore, by characterizing the H3K27Ac in matched tumor samples collected pre- and post-ENZA, we can interrogate the impact of AR activity on H3K27Ac." (PMID 33975627, 2021). "Conversely, molecular apocrine tumors, defined as AR- and FOXA1-expressing tumors that frequently harbor PIK3CA mutations, were more frequently associated with a “cold tumor” phenotype (i.e., low TIL density and absence of PD-L1 expression)." (PMID 33673133, 2021). "The heterogeneity of tumor evolution from AR-positive, adenocarcinoma to AR-negative, neuroendocrine prostate cancer (NEPC) is not fully characterized." (PMID 34099734, 2021). "We propose that G3BP1high may represent a PCa patient cohort characterized by compromised tumor-suppressive SPOP ubiquitin ligase and hyper-activated AR." (PMID 34795264, 2021). "Treatment with neither AR nor AD impacted tumor volume in BJ-HELTRas cells transduced with the empty vector neither tumor growth rate." (PMID 34203903, 2021). "In this context, AR activation stimulates proliferation and progression of HER2-enriched and TNBC subtypes, and combinatorial AR and HER2/mTOR inhibition synergistically reduces proliferation and tumor growth in mice." (PMID 34680352, 2021). "Again, NSC14466 exhibited similar anti-tumor abilities against both AR-positive (C4-2) and AR-negative (DU145 and PC3) cell lines in the same experimental setting." (PMID 34439974, 2021). "Using single-cell RNA-sequencing to perform an unbiased assessment of the cellular landscape of human prostate, we identify a subset of tumor-enriched androgen receptor-negative luminal epithelial cells with increased expression of cancer-associated genes." (PMID 34936871, 2021). "Increased AR expression in both human and rodent HCC tumours has been reported." (PMID 33574348, 2021). "The tumor volume in the AAV-PCBP1-AS1 group began to decline on the 22nd day, and subsequent immunohistochemistry also confirmed that after knocking down PCBP1-AS1, tumor AR, AR-V7, and Ki-67 expressions were significantly reduced." (PMID 34545063, 2021). "GT0918 significantly inhibited the AR-positive MCF-7 and BT474 tumor growth." (PMID 34392453, 2021). "Despite AR being present and nuclear in the majority of patients with residual disease as previously observed, we did not identify a significant contribution of known AR-driven mechanisms, a key feature of progressive CRPC, to acute tumor persistence." (PMID 34322653, 2021). "Also, azacytidine can restore AR expression in AR-negative PC3 cells and azacytidine treatment followed by the antiandrogen bicalutamide blunts in vivo tumor growth." (PMID 33420371, 2021).
tumor (continued). "This is demonstrated by the sequential assembly of Prostate cancer associated non-coding RNA 1 (PRNCR1) and lncRNA prostate cancer gene expression marker 1 (PCGEM1) with the androgen receptor (AR), the MEG3 structure required for its tumor suppressive function." (PMID 34504983, 2021). "However, enzalutamide treatment in PC346C-DCC-K tumour bearing mice did lower the PSA plasma levels, suggesting effective inhibition of the AR pathway (P<0·001, T-test)." (PMID 34749299, 2021). "Intriguingly, integrin α6 promotes survival and serves as a direct transcriptional target of the androgen receptor once the tumor fails to respond to androgen deprivation." (PMID 34576132, 2021). "AR (p = 0.053) and KRT5 (p = 0.029) mRNA expression was negatively correlated with tumor grade." (PMID 34209360, 2021). "In the study of oestrogen (ER) and progesterone (PR) receptor-negative tumours, attention is currently focused on cases that express androgen receptor (AR)." (PMID 33534004, 2021). "Nonetheless, there seems to be no indication of tumor-promoting effects of estrogens or progestogens on AR positive TNBC, which is the main concern when prescribing these drugs in cancer survivors." (PMID 34063736, 2021). "AR activity in residual tumour foci was not positively correlated with aldo-keto reductase family 1 member c3 expression, an enzyme-encoding gene whose expression drives intratumoral androgen synthesis in CRPC." (PMID 35008330, 2021). "On the contrary, in other studies, PDL1 expression on tumor cells and on TILs was not significantly different between AR-negative and AR-positive tumors, but a higher rate was observed in the AR-positive and FOXA1-negative subgroups." (PMID 33915941, 2021). "This reciprocal relationship persists in localized prostate cancer, where KLF5 expression is low/absent and tumor cells have an AR-positive luminal identity." (PMID 34737261, 2021). "The main role of AR activation is not the suppression or induction of gene expression, and consequently, it is difficult to find a scenario in which tumor growth can be stopped by targeting these receptors." (PMID 34831054, 2021). "Notably, tumor samples showed that interaction between OCT4 and AR was dramatically decreased, although ribavirin treatment decreased OCT4 protein levels in the nucleus of tumor cells." (PMID 34145268, 2021). "Selective accumulation of these histone marks is found at the AR-bound enhancers of M-phase cell cycle genes, such as CDK1 and UBEC2, in CRPC tissues and cell models when compared to androgen-dependent cell lines and tumor tissue samples." (PMID 34283056, 2021). "In an ER+ BC context, the downregulation of AR expression by decreased levels of ADPN would promote tumor growth because the AR would not be enabled to inhibit ER signaling." (PMID 34066328, 2021). "Subcutaneously administered 35 reduced tumor weights and degraded full-length AR and AR-SV (AR-V7) in 22RV1 cells, unlike 3, and further suppressed PSA in LNCaP (T877A) tumors." (PMID 33672769, 2021). "Another AR-bypass pathway is the activation of the AKT-mTOR pathway by p66Shc, which is an oxidase previously shown to promote androgen-independent cell growth through generation of reactive oxygen species (ROS) and being elevated in PCa tumor samples." (PMID 33810413, 2021). "While the reduction in tumor volume following treatment with high concentrations of 10 mg/kg Dutasteride was nonsignificant, no changes in AR, caspase‐3, cleaved caspase‐3, and Ki‐67 expression were observed." (PMID 34008909, 2021). "Isorhamnetin, kaempferol, FA, calycosin, hederagenin might play an anti-tumor role through targeting AKT1, CDK1 TYMS, MAPK3, AR, respectively." (PMID 34955857, 2021). "The therapeutic effect was more robust in the AR-positive 22Rv1 cells than in the AR-negative PC-3 cells, as the tumor inhibition rates were roughly 80% and 55% in 22Rv1 and PC-3 tumors, respectively." (PMID 34830961, 2021).
tumor (continued). "Here enzalutamide suppressed AR signalling, although tumour growth was not impacted, which reflected the treatment resistant phenotype of the CRPC models." (PMID 34749299, 2021). "The AR signal pathway is complicated in the occurrence and development of HCC 5, and most research results indicate that AR promotes tumorigenesis in the early stage of HCC 6 and inhibits tumor progression in the late stage 7." (PMID 33753989, 2021). "Additionally, unlike vehicle‐treated castrated samples, IVM‐treated samples demonstrated reduced PSA levels, tumor growth, p‐CAMKK2/p‐p38/p‐Hsp27 axis activity, and AR levels compared with pre‐castration samples." (PMID 33709547, 2021). "Contrary to its tumor suppressor role, some studies demonstrated that NKX3.1 may act as a pro-survival factor in prostate in collaboration with AR." (PMID 33884281, 2021). "Based on genetic aberrations of AR or the increased synthesis of androgens (in the tumor microenvironment [TME]) or adrenal androgen precursors, it has been reported that AR expression is increased and that AR signaling is consistent with the castration level of androgens in patients with mCRPC." (PMID 33807895, 2021). "NE tumor cells are androgen-independent and do not express AR, therefore, they do not respond to therapies directed to the AR pathway." (PMID 34684723, 2021). ": Our study demonstrates that cabazitaxel efficacy can be improved by simultaneous blocking of AR signalling by enzalutamide, even if AR targeted treatment no longer affects tumour growth." (PMID 34749299, 2021). "Overall, we conclude that combining enzalutamide and cabazitaxel treatment showed superior anti-tumour efficacy compared to cabazitaxel without targeting AR signalling." (PMID 34749299, 2021). "The secreted levels of the main activator of AR testosterone were not different between ccRCC and pRCC or based on tumor size, and were in the normal range (males 8.4–28.7 nmol/L, females 0.5–2.6 nmol/L)." (PMID 34440475, 2021). "Moreover, AR can upregulate the expression of EZH2 and CCRK, and subsequently activate β-catenin, thereby promoting tumor CP." (PMID 34907204, 2021). "AR expression in the relapsed tumor was lower than in the untreated tumor with some cells or regions expressing little or no receptor." (PMID 34575033, 2021). "Immunohistochemistry showed downregulation of BXDC2 expression in tumor (vs. non-neoplastic urothelium), higher grade/stage tumor (vs. lower grade/stage), and AR-positive tumor (vs. AR-negative)." (PMID 33652650, 2021). "As recruitment was not suspended between stage 1 and 2, 26 patients with AR+ tumours had been recruited; ORR within the first 26 AR+ patients was 1/26 (3.9%)." (PMID 33854564, 2020). "The cytotoxic, anti-inflammatory, anti-angiogenic, and neuroprotective activity of compounds 3–7, 9–12, 14–20, and 22–26, as well as their effect on androgen receptor-regulated transcription was evaluated in vitro in human tumor and non-cancerous cells." (PMID 33322046, 2020). "Furthermore, KLF5 and AR interacted with each other to regulate transcription of AR target genes (e.g., MYC, CCND1, and PSA) to promote cell proliferation and tumor growth." (PMID 32245249, 2020). "In vivo analysis revealed that it significantly attenuated tumor growth in AR-positive xenografted mice than in AR-negative xenografted mice." (PMID 33584291, 2020). "ER-positive/AR-positive (ER+/AR+) tumours demonstrated better OS than ER-positive/AR-negative (ER+/AR-) tumours(p = 0.015)." (PMID 32928183, 2020). "According to the result of animal experiment, AR negative tumor gained more T cell infiltrated than AR positive tumor when treated with PD-L1 inhibitor." (PMID 32579541, 2020). "TIL density, PD-L1 expression on tumor cells and PD-1 expression on TILs were not significantly different between AR+ and AR− tumors." (PMID 32429078, 2020).